APPL1 (adaptor protein, phosphotyrosine interacting with PH domain and leucine zipper 1)
Diseases named in the same sentence as APPL1 in open-access papers (continued):
Sharing a sentence is not in itself a finding about the gene and the disease.
Aleutian disease (1 paper, 2024). "From this, we identified several candidate genes contributing to the growth and feed efficiency (ARID1B, APPL1, TOX, and GPC5), reproduction (GRM1, RNASE10, WNT3, WNT3A, and WNT9B), pelt quality (MYO10, and LIMS1), and Aleutian disease tests (IFNGR2, APEX1, UBE3A, and STX11)." (PMID 38167844, 2024).
arteriosclerosis (1 paper, 2021). A vascular disorder characterized by thickening and hardening of the walls of the arteries. "As an upstream gene of AMPK, APPL1 regulates the inflammatory response of cells, antioxidation, and arteriosclerosis." (PMID 33841160, 2021).
Autoimmunity (1 paper, 2013). The occurrence of an immune reaction against the organism's own cells or tissues. "We could detect expression of both APPL1 and APPL2 in small intestinal biopsies and a significantly lower expression of APPL2 was detected in the CD autoimmunity cases as compared to controls." (PMID 23936387, 2013).
brain tumors (1 paper, 2013). "To test the potential involvement of APPL proteins in growth or progression of brain tumors, we first checked the level of APPL1 and APPL2 in protein extracts isolated from twenty five snap frozen human GBM samples." (PMID 22989406, 2013).
carbohydrate metabolism disorders (1 paper, 2020). "The genotyping results and glucose level data obtained from the general-population group and patients with carbohydrate metabolism disorders suggest that rs11544593 (located in the APPL1 gene) may contribute to earlier onset of carbohydrate metabolism disorders." (PMID 32854233, 2020).
cardiomyopathy (1 paper, 2021). A disease of the heart muscle or myocardium proper. "Laboratory manipulations of APPL1 demonstrate protection against high-fat diet-induced cardiomyopathy in rodents and APPL2 is responsible for dietary regulation, cold-induced thermogenesis, and cold acclimation (uniprot.org)." (PMID 33686424, 2021).
colorectal cancer (1 paper, 2013). A primary or metastatic malignant neoplasm that affects the colon or rectum. "Finally, APPL1 may also act as a proapoptotic factor by interacting with DCC (deleted in colorectal cancer) and enhancing the DCC‐induced apoptosis in colorectal cancer cells." (PMID 22989406, 2013).
complication (1 paper, 2016). Any disease or disorder that occurs during the course of, or because of, another disease, treatment, or procedure. "Our research suggests that adiponectin and the APPL1-AMPK-PPARα axis are important targets to interpret the cell protection mechanism of GLP-1, and this axis may be a potential target to prevent diabetic cardiovascular complications in the future." (PMID 26759813, 2016).
dementia (1 paper, 2023). Loss of intellectual abilities interfering with an individual's social and occupational functions. "Of these significantly positively correlated autoantibodies, five were differentially expressed in dementia and included CL1A, CBFA2T3, PKLR, APPL1, and NUDT2, whilst two were dysregulated in MCI including ABI1 and NUDT2." (PMID 38107644, 2023).
endometriosis (1 paper, 2023). The growth of functional endometrial tissue in anatomic sites outside the uterine body. "Seven genes, namely, APPL1, CSNK2A1, ERG, KDM4A, SMARCC1, SUZ12 and TRIM25, were selected to establish the diagnostic model for endometriosis, and a nomogram was constructed based on them." (PMID 36860677, 2023).
gastric cancer (1 paper, 2017). A primary or metastatic malignant neoplasm involving the stomach. "Expression of APPL1 is correlated with clinicopathologic characteristics and poor prognosis in patients with gastric cancer." (PMID 28415720, 2017).
hematoma (1 paper, 2022). A hematoma is a collection of blood from a vascular structure into an extravascular space. "AdipoR1-mediated activation of the APPL1/LKB1/AMPK/PPARγ pathway had a critical role in the M1 to M2 transformation, as well as in the process of hematoma resolution." (PMID 35720361, 2022).
hemorrhage (1 paper, 2022). Loss of blood from the vascular compartment to the exterior or into nonvascular body space as a result of rupture or severance of the blood vessels. "In all, we propose that APN works as a potential therapeutic agent to ameliorate the inflammatory response following GMH by enhancing the M2 polarization of microglia via AdipoR1/APPL1/AMPK/PPARγ signaling pathway, ultimately attenuating inflammatory brain injury induced by hemorrhage." (PMID 35720361, 2022).
Hepatic steatosis (1 paper, 2013). Steatosis is a term used to denote lipid accumulation within hepatocytes. "The impact of APPL1 and APPL2 SNPs on liver damage and hepatic steatosis severity has been also evaluated." (PMID 23977033, 2013).
insulinoma (1 paper, 2017). "Previous studies observed high APPL1 expression in C2C12 myotubes, insulinoma cells, L6 cells; moderate expression was detected in HEK293, mouse hepatocytes, while low expression was found in mouse brain, skeletal muscle, fat, heart, spleen and to a lesser extent, pancreas and kidney tissues." (PMID 28415720, 2017).
osteosarcoma (1 paper, 2017). A usually aggressive malignant bone-forming mesenchymal neoplasm, predominantly affecting adolescents and young adults. "To detect the arrival and departure events of individual APPL1 molecules at early endosomes, we transiently transfected human U2OS osteosarcoma cells with a C-terminal green fluorescent protein (GFP) fusion of APPL1 (APPL1–GFP)." (PMID 28071667, 2017).
ovarian carcinoma (1 paper, 2013). A malignant neoplasm originating from the surface ovarian epithelium. "Rab5a being activated by Appl1 is significantly overepressed in ovarian cancer and is connected with lung, hepatocellular and stomach carcinomas." (PMID 23874428, 2013).
renal carcinoma (1 paper, 2023). A carcinoma arising from the epithelium of the renal parenchyma or the renal pelvis. "APPL1 is expressed at low levels in Caki-1 cells, and we evaluated the effect on metastatic renal cancer cells by restoration to overexpression of APPL1." (PMID 36846720, 2023).
Sepsis (1 paper, 2021). Sepsis is defined as life-threatening organ dysfunction caused by a dysregulated host response to infection. "Since intraperitoneal injection of LPS is also known to induce noncanonical inflammasome via caspase-11 in the immune cells of mice, the exact mechanism whereby APPL1 controls sepsis and IL-1β production in animal model requires further investigation." (PMID 34789781, 2021).
subarachnoid hemorrhage (1 paper, 2018). A serious neurological disorder characterized by intracranial hemorrhage into the subarachnoid space. "NT-1 also activated APPL1-AKT signing pathway via combining with DCC receptor to reduce apoptosis after subarachnoid hemorrhage in rats." (PMID 30227858, 2018).
type 1 diabetic (1 paper, 2021). "Furthermore, APPL1 has a protective role in the pancreas by diminishing islet inflammation and β-cell apoptosis in STZ-induced type 1 diabetic mice." (PMID 34960104, 2021).
tumor (7 papers, 2013 to 2024). "In this study, we performed bioinformatics analysis based on the TCGA, UALCAN, TIMER, and TISIDB databases and found that APPL1 was downregulated in KIRC tumor tissues relative to adjacent normal tissues." (PMID 36846720, 2023). "We found that the expression of APPL1 was significantly downregulated in KIRC tumor tissues compared with adjacent normal tissues." (PMID 36846720, 2023). "Meanwhile, the trend of protein APPL1 expression in KIRC tumor from CPTAC cohort was consistent with the mRNA level (∗∗∗p < 0.001)." (PMID 36846720, 2023). "The results showed that APPL1 mRNA expression of tumor tissues was significantly lower than that of adjacent normal tissues (∗∗p < 0.01 and ∗∗∗p < 0.001)." (PMID 36846720, 2023). "To explore the roles of APPL1 in tumor, we analyzed the expression level of APPL1 mRNA in various human tumor tissues via the Tumor Immune Estimation Resource (TIMER2.0) online database." (PMID 36846720, 2023). "Previous studies have shown that APPL1 can inhibit cell migration via inhibiting activation of AKT pathway in tumor." (PMID 36846720, 2023). "We found that APPL1 expressed in the cytoplasm was significantly downregulated in tumor tissues relative to normal adjacent tissues (∗∗∗p < 0.001)." (PMID 36846720, 2023). "However, the effects of APPL1 expression on tumor Treg cell infiltration and correlation with poor prognosis have not been reported in KIRC." (PMID 36846720, 2023). "Low expression of APPL1 may adapt to tumor malignant progression by reducing oxygen-consuming metabolism and regulate tumor immune infiltration and chemotherapy resistance." (PMID 37664173, 2023). "We confirmed that expression level of APPL1 may affect the Treg cell infiltration (or exhausted T cells) in KIRC via downregulated the processes of oxygen-consuming metabolism in tumor microenvironment." (PMID 36846720, 2023). "The APPL1 was significantly downregulated with tumor progression in KIRC tissues and might lead to increased infiltration level of Treg cells." (PMID 36846720, 2023). "In this study, we integrated multiple bioinformatics methods based on database online to explore whether APPL1 affects tumor Treg infiltration and try to find its correlation with poor prognosis in KIRC patients." (PMID 36846720, 2023). "Interestingly, APPL1, as an adaptor protein with an important role in tumor promotion, has been reported to mediate adiponectin signaling by binding to adiponectin receptors." (PMID 28415720, 2017). "In addition, the expression levels of APPL1 in KIRC tumor cell lines Caki-1 and 769P were significantly lower than that of HK-2 cells (a normal proximal tubular cell line) (∗p < 0.05 and ∗∗p < 0.01), and this result was consistent with the gene expression distribution from CCLE database." (PMID 36846720, 2023). "The infiltrating T cells could have some typical phenotype that may be closely related to the tumor metabolic microenvironment in KIRC, but this study has not yet further explored the molecular mechanism of the effect of APPL1 expression on T cell phenotype transformation in tumor microenvironment." (PMID 36846720, 2023). "Thus, expression level of APPL1 may be correlated with change of tumor microenvironment in KIRC." (PMID 36846720, 2023). "Therefore, downregulation of APPL1 expression may contribute to tumor cell metastasis in KIRC." (PMID 36846720, 2023). "In addition, the expression level of APPL1 was negatively correlated with Treg cell infiltration and chemotherapy sensitivity, which indicated that APPL1 may regulate the tumor immune infiltration and chemotherapy resistance by decrease oxygen-consuming metabolic process in KIRC." (PMID 36846720, 2023). "Based on the difference of APPL1 protein expression between Caki-1 and 786O cells, we speculate that the metastasis of KIRC tumor cells may be related to the expression level of APPL1." (PMID 36846720, 2023).
tumor (continued). "Our results revealed that over 40% among 25 cases of human GBM appear to have a high level of APPL2 protein but not APPL1 when compared to non‐tumor tissue." (PMID 22989406, 2013).
cancer (6 papers, 2015 to 2024). A tumor composed of atypical neoplastic, often pleomorphic cells that invade other tissues. "In the case of normal tissue stained with the antibody against APPL1, compared to cancerous tissue, derived from the same patient, there was more intense staining in the case of the cancer tissue." (PMID 39267821, 2024). "The functional importance of nuclear TβRI-ICD is supported here by the finding that TGFβ-induced cancer cell invasion was suppressed after knockdown of APPL1 and APPL2." (PMID 26583432, 2016). "Nuclear TβRI-ICD has been found to promote the invasion of various cancer cells and as APPL proteins was found to be crucial for its nuclear translocation, we investigated the role of APPL1 and APPL2 in TGFβ-induced invasiveness in cancer cells." (PMID 26583432, 2016). "Future studies in larger clinical materials will be important to evaluate the clinical value of the herein reported APPL1-TβRI-ICD complex as a potential prognostic marker in tissues from patients with cancer." (PMID 26583432, 2016). "Quantitative real-time polymerase chain reaction (qRT-PCR) analysis showed that transcription of the cancer-associated matrix metalloprotease 2 (MMP2) and MMP9 decreased after silencing of APPL1 and APPL2." (PMID 26583432, 2016). "Because the interaction between APPL1 and TβRI is important during cancer progression, we investigated whether APPL proteins affect proliferation or survival of PC-3U cells." (PMID 35853811, 2022). "We have reported that the intracellular domain (ICD) of TGFβ receptor (TβR) I is cleaved by proteolytic enzymes in cancer cells, and then translocated to the nucleus in a manner dependent on the endosomal adaptor proteins APPL1/2, driving an invasiveness program." (PMID 35853811, 2022). "In normal prostate tissue, APPL1 was expressed only in basal epithelial cells but not in luminal cells, whereas in malignant prostate tissues APPL1 was expressed in all cancer cells." (PMID 26583432, 2016). "To further elucidate the role of APPL1 in cancer, we examined the expression and localization of APPL1 in normal and malignant prostate tissue by immunohistochemistry, as aberrant endocytosis of growth factor receptors has been found to be occur during cancer initiation and progression." (PMID 26583432, 2016). "The changes in APPL1 (3p21), RAB5A (3p24) and EEA1 (12q22) and RAB4A (1q42) in PIN or primary cancer tissue compared to their expression in non-malignant tissue may discriminate metastatic tissue and provide an avenue for monitoring disease progression." (PMID 26473288, 2015).
infection (2 papers, 2021). The state of being infected such as from the introduction of a foreign agent such as serum, vaccine, antigenic substance or organism. "However, at later times of infection, the proportion of cells with APPL1 accumulation in the juxtanuclear area increased." (PMID 34440603, 2021).
APPL1 also shares sentences with these, for which no sentence is quoted: breast carcinoma (5 papers); atherosclerosis (3); steatosis (2); brain injury (1); cerebral amyloid angiopathy (1); Cerebral ischemia (1); cholangiocarcinoma (1); Down syndrome (1); endothelial dysfunction (1); Glucose intolerance (1); hepatocellular carcinoma (1); Huntington disease (1); hyperlipidemia (1); injury (1); liver cancer (1); Lowe Syndrome (1); maturity-onset diabetes of the young (1); metabolic disorders (1); metabolic syndrome (1); metastatic disease (1); neurodegenerative disease (1); Parkinson’s (1); postmenopausal osteoporosis (1); prostate intraepithelial neoplasia (1); prostate tumour (1); Renal Clear Cell Carcinoma (1); stomach carcinomas (1).